ALB (albumin)
Diseases named in the same sentence as ALB in open-access papers (continued):
Sharing a sentence is not in itself a finding about the gene and the disease.
preeclampsia (continued). "A recent study evaluated the role of the fibrinogen-to-albumin ratio (FAR) as a novel inflammatory marker in preeclampsia and found that FAR is a useful marker for predicting disease severity." (PMID 41517251, 2025). "In the current study, the analytes identified as independent predictors of preeclampsia were the oxidized LDL/albumin ratio, lymphocyte levels, urine iodine concentration, serum potassium/magnesium ratio, TSH, and FPG." (PMID 40282890, 2025). "Our findings align with previous research demonstrating the roles of fibrinogen and albumin in preeclampsia pathophysiology." (PMID 41246030, 2025). "In this study, we employed the PubMed database to search for articles that assessed the antioxidant properties of albumin, with a specific focus on obstetric diseases, particularly preeclampsia." (PMID 39857389, 2025). "Understanding the antioxidant properties of albumin not only provides new insights into the pathophysiology of preeclampsia but also opens avenues for innovative therapeutic strategies targeting oxidative damage in obstetric and gynecological disorders." (PMID 39857389, 2025). "Although the uric acid-to-albumin ratio (UAR) has previously been evaluated in preeclampsia in relation to disease severity, the LDH-to-albumin ratio (LAR) has not been reported." (PMID 41517251, 2025). "Potential treatment strategies involving albumin for preeclampsia include albumin replacement and prevention of renal excretion." (PMID 39857389, 2025). "The Canadian Society of Obstetrics and Gynecology (SOGC) includes a serum albumin level below 2 g/dL as a possible severity criterion in preeclampsia, although current evidence remains limited, and this topic continues to be an area of active research." (PMID 40648529, 2025). "In our cohort, serum albumin levels were significantly lower among women with severe preeclampsia compared to those with mild disease, and a threshold of 2.3 g/dL demonstrated good sensitivity and specificity in discriminating PE severity." (PMID 40648529, 2025). "This study addresses an important clinical gap by investigating serum albumin as a potential complementary marker for preeclampsia severity, in a context where reliable biomarkers remain limited." (PMID 40648529, 2025). "Our conclusion was that low serum albumin levels cannot be used either as a significant predictor of the severity of preeclampsia or for the occurrence of these complications." (PMID 40648529, 2025). "Previous studies have demonstrated that albumin modulates inflammatory responses, another component of the pathophysiology of preeclampsia." (PMID 39857389, 2025). "Urine albumin to creatinine ratio at both 5 and 10 weeks postpartum was not significantly different between mice that had a normal pregnancy and mice that had a preeclampsia-like pregnancy." (PMID 40425613, 2025). "Reports on albumin as an antioxidant in patients with preeclampsia are still limited but are gradually emerging." (PMID 39857389, 2025). "Albumin serves as an antioxidant in preeclampsia, scavenging free radicals and maintaining redox homeostasis." (PMID 39857389, 2025). "As for serum TSH, the low sensitivity and specificity of the lymphocyte percentage and the oxidized LDL/albumin ratio preclude their potential use as screening tests for preeclampsia." (PMID 40282890, 2025). "In cases where preeclampsia develops and renal impairment occurs, albumin replacement is swiftly excreted in the urine, raising uncertainties about its efficacy." (PMID 39857389, 2025). "Recently, the antioxidant properties of albumin have gained attention, promoting our focus on its role in the pathogenesis of preeclampsia." (PMID 39857389, 2025). "In contrast, in women with preeclampsia, urinary albumin excretion decreases rapidly, and postpartum renal dysfunction improves dramatically." (PMID 39857389, 2025).
preeclampsia (continued). "Several studies have shown that maternal albumin levels measured at the onset of disease tend to be lower (p < 0.001) in women with preeclampsia compared to those with normal pregnancies." (PMID 39408980, 2024). "Systemic inflammation, which is a feature of preeclampsia, can alter the hepatic production of albumin." (PMID 39408980, 2024). "Two such markers are fragments of SERPINA1 and albumin, upregulated in women with preeclampsia but downregulated in gestational hypertension." (PMID 36909346, 2023). "Age, white blood cells (WBC), platelet, creatinine, albumin, uric acid, aspartate aminotransferase, alanine aminotransferase, international normalized ratio, and prothrombin time were significantly related to preeclampsia severity." (PMID 37978251, 2023). "An expecting woman has high blood pressure during preeclampsia, which is higher than or equal to 140/90 mmHg of systolic and diastolic blood pressure, as well as albumin protein in the urine." (PMID 36483900, 2022). "The FFA/albumin ratio is increased in women with preeclampsia leading to further lipolytic activity, thereby more endothelial FFA uptake and esterification to TG." (PMID 36171850, 2022). "Pregnant women with preeclampsia are often accompanied by decreased proteinuria and plasma albumin levels and are prone to edema of the limbs and skin, as well as edema of the myometrium, which can lead to weak uterine contractions." (PMID 35432840, 2022). "In pregnant women with preeclampsia, systolic and diastolic pressure, proteinuria, alanine aminotransferase, lactate dehydrogenase, blood urea nitrogen, and albumin levels were significantly higher than those in healthy pregnant women." (PMID 36123601, 2022). "Survival rate was associated with gestational age at birth, initial diagnosis time, birthweight, Apgar score, initial albumin and pH levels, and gestational hypertension." (PMID 35455574, 2022). "We identified three specific oxidative stress biomarkers [ischemia-modified albumin (IMA), uric acid (UA), malondialdehyde (MDA)], which exhibited reliable diagnostic odd ratio (DORs) indicative of their diagnostic potential in preeclampsia." (PMID 35658944, 2022). "Further, the survivors had significantly different birth bodyweights, Apgar scores, initial albumin and pH levels, and rates of gestational hypertension." (PMID 35455574, 2022). "Women who developed either preeclampsia or eclampsia showed an increased cerebral spinal fluid to albumin ratio, indicating injury to the blood-brain barrier, compared to women with normotensive pregnancies." (PMID 36324311, 2022). "Proteoforms of ceruloplasmin, immunoglobulin free light chains, SERPINA1, albumin, interferon-inducible protein 6–16, and β-amyloid were all found in the urine of women with preeclampsia when a Congo red dot test was positive." (PMID 36324311, 2022). "In one study that had previously investigated the CSF/plasma albumin ratio, 15 women with preeclampsia and 15 women with normotensive pregnancies were included." (PMID 34831266, 2021). "In particular, women with eclampsia but also women with preeclampsia showed an increase in the CSF to plasma albumin ratio compared to normotensive women." (PMID 34831266, 2021). "The independent risk factors of ARC were heavier, greater gestational age, higher albumin level, fewer caesarean section, severe preeclampsia and vasoactive drug; more infection, hypertriglyceridemia and acute pancreatitis." (PMID 34177564, 2021). "In our study, 24-h proteinuria was negatively correlated with albumin, it means we cannot deny the role of 24-h proteinuria in predicting adverse outcomes in patients with preeclampsia." (PMID 33990220, 2021). "Women with preeclampsia showed a 1.9-fold increase in the CSF/plasma albumin ratio (95% CI 1.01–3.65, p = 0.048) compared to normotensive women." (PMID 34831266, 2021).
preeclampsia (continued). "The significant independent factors for the occurrence of ARC were heavier, greater gestational age, higher albumin level, fewer caesarean section, severe preeclampsia and vasoactive drug; more infection, hypertriglyceridemia and acute pancreatitis (p < 0.05)." (PMID 34177564, 2021). "Age, HCY, CYC, uric acid, total bile acid, BMI, and albumin were independent predictors of gestational hypertension and preeclampsia." (PMID 32245416, 2020). "Preeclampsia is defined as gestational hypertension with significant proteinuria (> 0.3 g/24 h or an albumin-to-creatinine ratio ≥ 30 mg/mmol)." (PMID 32170412, 2020). "Serum Albumin/Globulin ratio, Creatinine, fT4 varied significantly between PE (ePE and lPE) and lCON (P < 0.05), indicating the feature of preeclampsia and normal pregnancy." (PMID 32194641, 2020). "In the study focused on the relationship between the serum albumin and the preeclampsia, it was found that women in the preeclampsia group displayed significantly lower level of serum albumin than those in the normal group." (PMID 31900124, 2020). "Previous observational studies demonstrated that the random urine albumin/creatinine ratio was a poor predictor for a proteinuria of > 2 g/day in patients with preeclampsia." (PMID 31387546, 2019). "The ionized magnesium fraction and serum albumin levels of the normal pregnancy were significantly higher than those of the preeclampsia group (26.28 ± 2.3% vs. 23.95 ± 4.7% p = .04 and 3.55 ± 0.2 g/dL vs. 3.32 ± 0.3 g/dL, p < .001, respectively)." (PMID 29318926, 2018). "The Student’s T-test was employed to compare the levels of total magnesium, ionized magnesium, ionized magnesium fraction and serum albumin among women with normal pregnancy and preeclampsia." (PMID 29318926, 2018). "Factors which were found different between the normal pregnancy and preeclampsia groups included serum albumin levels and the ionized magnesium fraction." (PMID 29318926, 2018). "This isoform induced late-onset preeclampsia with only a moderate increase in urinary albumin excretion in mice." (PMID 25860260, 2015). "Other studies also reflected socio-economic status and antenatal care provision plays the same role as biochemical markers of preeclampsia like urine albumin." (PMID 25824330, 2015). "Materials and methods: It is a prospective study carried out on 125 pregnant women with preeclampsia after 20 weeks of gestation having urine albumin >1 using dipstick test." (PMID 25628723, 2014). "The 24-hr urinary albumin excretion, another defining feature of preeclampsia, was measured in pregnant rats." (PMID 25108313, 2014). "In another study proteomic profiling in urine samples from 284 women was analyzed and it was identified that specific fragments of serpina-1 and albumin have potential to be used as biomarkers of preeclampsia." (PMID 24829801, 2014). "The titers of FT3 are significantly related to the decreased plasma albumin concentration in preeclampsia." (PMID 25242974, 2012). "Furthermore, a one-unit decrease in albumin level resulted in a 1.294-fold increase in the odds of developing preeclampsia." (PMID 41594281, 2026). "BACKGROUND: This study aimed to investigate the association between the albumin–bilirubin (ALBI) score and disease severity across the preeclampsia spectrum and to evaluate its relationship with perinatal outcomes, with particular emphasis on differences according to gestational age." (PMID 41975386, 2026). "In addition, we discussed the role of albumin in preeclampsia pathogenesis, diagnosis, and patient prognosis." (PMID 39857389, 2025). "In contrast, ischemia-modified albumin is a marker of preeclampsia." (PMID 39857389, 2025). "We discussed the role of albumin in preeclampsia pathogenesis, diagnosis, and patient prognosis." (PMID 39857389, 2025). "However, urinary albumin excretion was higher in patients with preeclampsia than in normal parturients." (PMID 39857389, 2025).
preeclampsia (continued). "The univariate logistic regression analysis showed that age, gravidity, parity, gestational age of diagnosis, iron supplementation, preeclampsia, edema, headache, dizziness, or blurred vision, albumin, ALT, creatinine, and lactate dehydrogenase were significantly associated with SMM (Table-IV)." (PMID 40735566, 2025). "Therefore, reduced serum albumin levels predict the increased production of oxygen-derived free radicals, resulting in a maternal vascular endothelial function in parturients with preeclampsia." (PMID 39857389, 2025). "Nevertheless, the HALP score calculated as [hemoglobin (g/L) × albumin (g/L) × lymphocytes (/L)]/platelets (/L) has been identified as an independent indicator for preeclampsia with severe features, predicting the development of such conditions with a sensitivity of 74.5% and a specificity of 81.3%." (PMID 39408980, 2024). "Elevated or altered albumin levels may serve as early indicators for potential complications, providing valuable insights for the early detection and management of preeclampsia and related conditions." (PMID 39408980, 2024). "Ischemia-modified albumin (IMA), uric acid (UA), and malondialdehyde (MDA) were associated with 3.38 (95% CI 2.23, 4.53), 3.05 (95% CI 2.39, 3.71), and 2.37 (95% CI 1.03, 3.70) odds ratios for preeclampsia diagnosis, respectively." (PMID 35658944, 2022). "In women with different types of hypertensive disorders of pregnancy (gestational hypertension, chronic hypertension, preeclampsia, and eclampsia), antioxidant markers (antioxidant activity, albumin, and total thiols) were decreased in all hypertensive groups compared to healthy pregnant women." (PMID 35883909, 2022). "In our study, the median CSF/plasma albumin ratio in women with preeclampsia was 5.2." (PMID 34831266, 2021). "In addition, the CSF/plasma albumin ratio was increased in preeclampsia as a measurement of blood–brain barrier impairment." (PMID 34831266, 2021). "Interestingly, women with preeclampsia had a lower CSF/plasma albumin ratio of 3.5 (IQR 2.9–5.1) compared to 5.21 (range 2.83–14.79) in our study." (PMID 34831266, 2021). "Women with preeclampsia had a median CSF/plasma albumin ratio of 3.02." (PMID 34831266, 2021). "Additionally, albumin’s modulation of inflammation may indirectly mitigate oxidative stress in the context of preeclampsia." (PMID 39857389, 2025). "The urinary iodine concentration, serum TSH, the oxidized LDL/albumin ratio and FPG, and lymphocytosis may be useful in the prediction of women at increased risk of preeclampsia among populations with iodine deficiency, micronutrient malnutrition, and recurrent infections, respectively." (PMID 40282890, 2025). "In addition, albumin is a large molecule and there might be other mechanisms of action causing increased permeability over the BBB in preeclampsia such as up-regulation of transporter proteins shown in animal studies." (PMID 33556141, 2021). "Therefore, the decreased albumin and the resulting decreased GlyA may have made the patients more vulnerable to preeclampsia." (PMID 31900124, 2020). "At present, there are insufficient data to recommend using the urinary albumin/creatinine ratio, but this may change when more research becomes available, such as the results of the DAPPA (Diagnostic Accuracy in Preeclampsia using Proteinuria Assessment, RCTN82607486) clinical trial." (PMID 32545523, 2020). "The lower concentrations of IMA than preeclampsia in normotensive pregnancies when compared with preeclamptic patients suggest that inflammation and endothelial cell activity in preeclampsia may alter the albumin molecule in the plasma of preeclamptic patients and may increase the levels of IMA." (PMID 32232820, 2020). "It appears that a significant increase in albumin-creatinine ratio (microalbuminuria) among preeclamptic group could possibly be an indication of renal pathology, an observation which may support the multiorgan dysfunction effect of preeclampsia as a disease." (PMID 30155474, 2018).
preeclampsia (continued). "SHAP summary plots consistently ranked LDH, albumin, and SBP_32_36 among the most influential predictors, reinforcing their biological plausibility and echoing recent applications of SHAP in preeclampsia and postpartum hemorrhage models." (PMID 41341133, 2025). "Asb4−/− female mice develop mild preeclampsia-like phenotypes during pregnancy, including increased systolic blood pressure (SBP) and urinary albumin excretion, as well as a decreased litter size." (PMID 39201703, 2024). "Between normal pregnant women and those with preeclampsia, there were significant differences in AST (p = 0.001), ALT (p < 0.001), total protein (p < 0.001), albumin (p = 0.047), and globulin (p < 0.001)." (PMID 37700972, 2023). "In the univariate logistic regression analysis, all the characteristics including age, WBC, platelet, creatinine, albumin, uric acid, AST, ALT, INR, and PT had a close relation with preeclampsia severity (all P < 0.05)." (PMID 37978251, 2023). "In this study, we identified several central genes closely related to ferroptosis in STB-EVs (ALB, NOX4, CDKN2A, TXNRD1, and CAV1) that are potential biomarkers related to ferroptosis in preeclampsia." (PMID 36343018, 2022). "In this investigation, we demonstrated numerous key genes (ALB, NOX4, CDKN2A, TXNRD1, and CAV1) that are expected to act as biomarkers for ferroptosis in STB-EVs of preeclampsia." (PMID 36343018, 2022). "The levels of hemoglobin (Hb), alanine transaminase (ALT), aspartate aminotransferase (AST), urea, and creatinine (Cr) were higher, while albumin (ALB) and platelet (PLT) was lower in preeclampsia pregnant women compared with normotensive pregnant women." (PMID 35185616, 2022). "In preeclampsia, there is a higher serum FFA to albumin ratio and increased LPL activity, resulting in enhanced endothelial uptake of FFA, which are further esterified and accumulated into triglycerides pools, secondary to a decrease in intracellular lipase." (PMID 35631313, 2022). "However, the low serum albumin levels may have resulted from nonspecific causes like illness or inflammation, and the change in serum albumin levels may have been a consequence of preeclampsia, not a cause." (PMID 29318926, 2018). "This may have suggested changes in other binding proteins in addition to albumin during pregnancy, mobilization of ionized magnesium into its complex form, or magnesium influx into cells, which may have played essential roles in pathophysiology of preeclampsia." (PMID 29318926, 2018). "The spot urinary protein to creatinine ratio and the albumin to creatinine ratio (ACR) have been studied in patients with renal disease, diabetes and preeclampsia to assess proteinuria." (PMID 28247485, 2017). "The negative correlation between albumin and ischemia-modified albumin observed in preeclampsia indicates the role of albumin as an oxidative stress scavenger." (PMID 39857389, 2025). "Albumin levels were significantly lower in the sPE group compared to both the control group and preeclampsia patients without severe features (p < 0.001)." (PMID 41517251, 2025). "On the contrary, in our study, neither serum total calcium levels nor albumin-corrected calcium levels of the preeclampsia group were similar to those of the control group." (PMID 39045952, 2024). "ALB, NOX4 and CAV1 are associate with the prosses of preeclampsia, and the other two genes (CDKN2A, TXNRD1) have not been linked directly to the occurrence of preeclampsia." (PMID 36343018, 2022). "In our study, there was no alteration in albumin quotient in preeclampsia vs normal pregnancy, supported by previous findings." (PMID 33556141, 2021). "Non-metabolomics methods have been used to predict preeclampsia from urine samples, focusing on urinary albumin to creatinine ratios as a measure of kidney function, and creatinine levels in urine." (PMID 26370975, 2015).